RNU7-40P (RNA, U7 small nuclear 40 pseudogene)
Synonyms: U7.40
Gene: Small nuclear RNA gene on chromosome 12 (56,352,387 to 56,352,450, reverse strand). Ensembl gene ENSG00000252206.
Homologues: Paralogues in human: RNU7-14P (88% identical), RNU7-23P (88% identical), RNU7-7P (88% identical), RNU7-11P (86% identical), RNU7-18P (86% identical), RNU7-25P (86% identical), RNU7-28P (86% identical), RNU7-3P (86% identical), RNU7-22P (84% identical), RNU7-2P (84% identical), RNU7-37P (84% identical), RNU7-45P (84% identical), and 141 more.